CIT (citron rho-interacting serine/threonine kinase)
Description:
Plays a role in cytokinesis. Required for KIF14 localization to the central spindle and midbody. Putative RHO/RAC effector that binds to the GTP-bound forms of RHO and RAC1. It probably binds p21 with a tighter specificity in vivo. Displays serine/threonine protein kinase activity. Plays an important role in the regulation of cytokinesis and the development of the central nervous system. Phosphorylates MYL9/MLC2.
Synonyms: CRIK; KIAA0949; STK21; CITK; MCPH17
Tractability: Small molecule: a high-quality ligand is known; it belongs to a druggable protein family. PROTAC: it is named in the literature on targeted protein degradation; ubiquitination databases record sites on it; its protein half-life has been measured; a small molecule that binds it is known.
Target class: Kinase; AGC protein kinase DMPK family; AGC protein kinase group; Enzyme; AGC protein kinase CRIK subfamily; Protein Kinase
Chemical probes: C3TD-879 (high quality)
Gene: Protein-coding gene on chromosome 12 (119,685,791 to 119,877,332, reverse strand). Ensembl gene ENSG00000122966.
Subcellular location: Cytoplasm
Subcellular location (Human Protein Atlas): Cytosol
Pathways (Reactome):
Signal Transduction: RAC1 GTPase cycle; RHO GTPases activate CIT; RHOA GTPase cycle; RHOB GTPase cycle; RHOC GTPase cycle
Gene Ontology:
Molecular function: PDZ domain binding; protein binding; protein kinase binding; protein serine/threonine kinase inhibitor activity; scaffold protein binding; transcription coactivator binding; protein serine/threonine kinase activity; ATP binding; protein kinase activity; protein serine kinase activity
Biological process: mitotic cytokinesis; negative regulation of hippo signaling; positive regulation of cytokinesis; generation of neurons; mitotic cell cycle; regulation of actin cytoskeleton organization
Cellular component: cytosol; membrane; cytoplasm
Genetic constraint (gnomAD): Loss-of-function variants: 71 observed, 244.92 expected, observed/expected ratio (o/e) 0.29, 90% interval 0.24 to 0.35. The upper end of that interval is the gene's LOEUF score, 0.35, which puts it in group 1 of 6, group 1 being the genes least tolerant of losing a copy. Missense variants: 1,812 observed, 2,524.6 expected, observed/expected ratio (o/e) 0.72, 90% interval 0.69 to 0.75. Synonymous variants: 907 observed, 972.9 expected, observed/expected ratio (o/e) 0.93, 90% interval 0.88 to 0.99.
Homologues: Orthologues: chimpanzee CIT (98% identical), macaque CIT (98% identical), rabbit CIT (98% identical), dog CIT (98% identical), pig CIT (97% identical), mouse Cit (97% identical), guinea pig CIT (96% identical), rat Cit (96% identical), tropical clawed frog cit (82% identical), zebrafish cita (72% identical), zebrafish citb (54% identical), Drosophila melanogaster sti (24% identical). Paralogues in human: CDC42BPB (21% identical), CDC42BPA (21% identical), ROCK2 (19% identical), ROCK1 (19% identical), CDC42BPG (18% identical).
Diseases named in the same sentence as CIT in open-access papers:
CIT is named in the same sentence as 36 diseases in open-access papers, as found by Europe PMC text mining. Sharing a sentence is not in itself a finding about the gene and the disease. The quoted sentences say what the papers report.
microcephaly (11 papers, 2011 to 2025). A congenital or acquired developmental disorder in which the circumference of the head is smaller than normal for the person's age and sex. "Biallelic CIT missense variants that disrupt kinase function (kinase-inactive [KI]) and loss-of-function (LOF) frameshift (FS) variants that destroy both kinase and scaffolding functions are the genetic basis of microcephaly and microlissencephaly, respectively." (PMID 39316437, 2024).
breast carcinoma (5 papers, 2012 to 2023). "CIT, a serine/threonine-protein kinase, functions together with Kif14 (its expression increased by more than four folds in the TCGA breast cancer samples) in cell division." (PMID 28212608, 2017). "For examples in Breast Cancer, CASK (calcium/calmodulin-dependent serine protein kinase) and CIT (rho-interacting, serine/threonine kinase 21) are ranked 161 and 115, and with a 2.88 and 3.06 fold change in gene expression of breast cancer tissues, respectively." (PMID 22952662, 2012). "Thus far, there are no reported connections between GALNT3 and CIT expression and breast cancer." (PMID 37391533, 2023).
colon carcinoma (5 papers, 2016 to 2021). "Overexpression of CIT has been observed in human ovarian cancer, hepatocellular carcinoma, colon cancer, and multiple myeloma." (PMID 32185224, 2020). "To investigate the role of CIT in human colon cancer, we knocked down CIT with lentivirus-mediated shRNA in RKO and HCT116 cell lines." (PMID 29069760, 2017). "We found that CIT knockdown inhibits proliferation and colony formation in the colon cancer cell lines RKO and HCT116." (PMID 29069760, 2017). "Our investigation of the mechanism indicates that CIT knockdown induces cell cycle arrest and apoptosis in colon cancer cells." (PMID 29069760, 2017). "Western blotting revealed that CIT protein levels were significantly up-regulated in 4 tested colon cancer tissues compared with matched adjacent normal tissues." (PMID 29069760, 2017). "In summary, we provide evidence that CIT is overexpressed in human colon cancer tissues and serves as a tumor promoter." (PMID 29069760, 2017). "Then, we knocked down CIT and found that CIT knockdown inhibited the proliferation and colony formation of colon cancer cells in vitro and reduced colon cancer cell growth in vivo." (PMID 29069760, 2017). "To investigate the function of CIT in colon cancer cell growth in vivo, we evaluated xenograft formation of HCT116 cells with/without stable CIT knockdown." (PMID 29069760, 2017). "In the present study, we demonstrate that citron rho-interacting, serine/threonine kinase 21 (CIT) promotes the growth of human colon cancer cells." (PMID 29069760, 2017). "CIT protein levels were up-regulated in five human colon cancer cell lines compared with the human colon mucosal epithelial cell line NCM460." (PMID 29069760, 2017). "Furthermore, the percentage of apoptotic cells was significantly up-regulated when CIT was knocked down in colon cancer cells." (PMID 29069760, 2017). "We first found that CIT was overexpressed in human colon cancer tissues." (PMID 29069760, 2017). "In this study, we show that CIT expression is markedly up-regulated in human colon cancer, indicating that CIT may facilitate the development of colon cancer." (PMID 29069760, 2017). "We found that CIT knockdown also induced cell cycle arrest in colon cancer cells." (PMID 29069760, 2017). "In colon cancer cells, CIT knockdown represses cellular proliferation and colony formation." (PMID 29069760, 2017). "We found that CIT knockdown induces cell cycle arrest and apoptosis in colon cancer cells." (PMID 29069760, 2017). "However, while CIT knockdown inhibits the G1/S transition in colon cancer cells, CIT knockdown does not inhibit the G2/M transition as is observed in hepatocellular carcinoma cells." (PMID 29069760, 2017).
hepatocellular carcinoma (5 papers, 2011 to 2022). A malignant tumor that arises from hepatocytes. "It is worth mentioning that the overexpression of CENPF and CIT, as is the case in this study, has been associated with different types of cancer such as cervical cancer, hepatocellular carcinoma, osteosarcoma, bladder cancer, and esophageal squamous cell carcinoma." (PMID 35831333, 2022). "CIT also regulates the G2/M transition in rat hepatocytes, and knocking down CIT inhibits the proliferation of hepatocellular carcinoma cells." (PMID 29069760, 2017). "Another study showed that the down-regulation of miR-486 mediates the up-regulation of CIT in hepatocellular carcinoma." (PMID 29069760, 2017). "CIT also regulates the G2/M transition in rat hepatocytes, and knocking down CIT inhibited the proliferation of hepatocellular carcinoma cells." (PMID 21698188, 2011). "The overexpression of CIT in human ovarian and hepatocellular carcinoma has also been observed." (PMID 32185224, 2020).
medulloblastoma (5 papers, 2020 to 2025). A malignant, invasive embryonal neoplasm arising from the cerebellum. "Recently, a study has found that inactivation of CIT significantly reduces RAD51, a factor that helps to repair DNA damage, thus causing accumulation of DNA damage in medulloblastoma cells and finally leading to apoptosis." (PMID 34305997, 2021).
bladder cancer (3 papers, 2020 to 2023). "In this study, we provided that higher mRNA and protein levels of CIT were significantly associated with aggressive phenotypes of bladder cancers and poorer prognosis." (PMID 32368300, 2020). "Five datasets including GSE13507, GSE31684, E-MTAB-1803, E-MTAB-4321 and TCGA-BLCA, were selected to research on the associations of CIT expression with clinical outcome of patients with bladder cancer." (PMID 32368300, 2020). "The upregulation of CIT could promote the growth of cancer cells, and was associated with a poor outcome in some cancers such as bladder cancer and pancreatic ductal adenocarcinomas." (PMID 37938151, 2023). "In conclusion, these findings indicated that overexpression of CIT was significantly related to the poor survival outcome in bladder cancers." (PMID 32368300, 2020). "We also measured CIT expression in bladder cancer cell lines according to different invasiveness." (PMID 32368300, 2020).
brain tumor (2 papers, 2021 to 2022). "Experiments involving CIT gene silencing in GBM cell lines and in gene-knockout mice could be carried out to understand what effect the gene has on brain tumor growth or other." (PMID 35877430, 2022).
COVID-19 (2 papers, 2022). A disease caused by infection with severe acute respiratory syndrome coronavirus 2. "Further studies are needed to investigate the effect of targeting CENPF and CIT as a possible therapeutic strategy to treat COVID-19." (PMID 35831333, 2022).
lung adenocarcinoma (2 papers, 2021 to 2022). A carcinoma that arises from the lung and is characterized by the presence of malignant glandular epithelial cells. "For example, high expression of P4HB as well as low expression of BTG2 and CIT was associated with poor overall survival of lung adenocarcinoma patients (p-value of log-rank test < 0.05)." (PMID 36138770, 2022).
Primary microcephaly (2 papers, 2021 to 2024). Head circumference below 2 standard deviations below the mean for age and gender at birth. "The discovery that hypomorphic CIT alleles are the basis of primary microcephaly highlighted a previously unappreciated role for CIT-K kinase activity as a determinant of brain size." (PMID 39316437, 2024).
prostate carcinoma (2 papers, 2012 to 2025). A carcinoma that arises from epithelial cells of the prostate gland. "In prostate cancer, E2F2 activated CIT expression through the Skp2‐p27 axis and conducted androgen deprivation therapy resistance." (PMID 39999286, 2025). "It is plausible that the requirement for CIT, GALK2, and PSKH1 varies depending upon the tumorigenic state since the mRNA levels of these kinases increase as prostate cancer progresses." (PMID 22761715, 2012). "This study demonstrates the applicability of lentiviral-based shRNA for conducting phenotypic screens and identifies MAP3K11, DGKD, ICK, CIT, GALK2, and PSKH1 as regulators of prostate cancer cell growth." (PMID 22761715, 2012). "This study further demonstrates the applicability of lentiviral based shRNA for conducting phenotypic screens to identify targets involved in a variety of biological processes, and establishes MAP3K11, DGKD, ICK, CIT, GALK2, and PSKH1 as regulators of prostate cancer cell growth." (PMID 22761715, 2012).
endometrial carcinoma (1 paper, 2022). A malignant tumor arising from the epithelium that lines the cavity of the uterine body. "Immunohistochemistry revealed ISH scores for four risk kinases (ALPK2, TTK, PTK6, and CIT) were significantly higher in endometrial carcinoma tissues than in healthy endometrium, which suggested that high expression of these genes may contribute to the progression of UCEC." (PMID 36158685, 2022). "Using univariate Cox regression and Least absolute shrinkage and selection operator (LASSO), seven kinases (ALPK2, CAMKV, TTK, PTK6, MAST1, CIT, and FAM198B) were identified to establish a prognostic model of endometrial cancer." (PMID 36158685, 2022).
esophageal squamous cell carcinoma (1 paper, 2021). Esophageal squamous cell carcinoma (ESCC) is a type of esophageal carcinoma (EC) that can affect any part of the esophagus, but is usually located in the upper or middle third. "This study aimed to investigate the role and potential regulatory mechanism of citron kinase (CIT) in esophageal squamous cell carcinoma (ESCC)." (PMID 34305997, 2021).
cancer (20 papers, 2014 to 2026). A tumor composed of atypical neoplastic, often pleomorphic cells that invade other tissues. "Phosphorylation of NDRG1, a regulator of the cytoskeleton that has been implicated in cancer migration and invasion, was dramatically downregulated following the suppression of CIT expression." (PMID 33499898, 2021). "In conclusion, the combined analyses of CIT mutations and mRNA expression in cancers, and the effects of its over-expression data in NIH3T3 cells, do not support the possibility of an oncogenic role for CIT-K." (PMID 27895316, 2016). "CIT is a critical protein with significant clinical relevance, particularly due to its overexpression in cancers such as bladder, breast, and colon, where it drives aggressive tumor phenotypes and poor prognosis." (PMID 41601480, 2026). "CIT (Citron rho-interacting serine/threonine kinase) regulates critical steps in cytokinesis, and its overexpression promotes cancer cell proliferation." (PMID 41246267, 2025). "CIT, a serine/threonine kinase, potentially regulates cancer development by phosphorylating downstream targets involved in apoptosis." (PMID 38102321, 2023). "Previously, studies have already identified CIT as a regulator of midbody and cell division, and nearly all studies on CIT functions in cancer focused the effects of CIT on cell cycle." (PMID 32185224, 2020). "We next wanted to develop a better understanding of how CIT mRNA expression varies in different cancers." (PMID 27895316, 2016). "CIT is a serine/threonine protein kinase involved in central nervous system development and cancer cells proliferation." (PMID 25981335, 2015). "CIT overexpression has been associated with cancers of various origin, likely through its kinase function that is, however, lost during chromosomal rearrangement in the FGFR2-CIT fusion." (PMID 34207779, 2021). "Thus, we have identified two types of transcripts: (a) transcripts that are not expressed in normal conditions and are gained in cancer (e.g. CIT, CCNE1) and (b) transcripts that gain an additional cancer-associated transcript (e.g. MTA3, ZFHX3)." (PMID 33499898, 2021). "Recently, the role of CIT in human cancer has been identified." (PMID 32185224, 2020). "In order to get the best representation of CIT mRNA expression in cancers, we collated data from all of the datasets available that compared cancer tissue versus the corresponding normal tissue and identified the datasets reporting significantly (p < 0.001) over- or under-expressed CIT mRNA." (PMID 27895316, 2016). "Upregulation of CIT promotes DNA replication and cancer cell proliferation." (PMID 26230496, 2015). "Citron Rho-interacting serine/threonine kinase (CIT) is a multifunctional member of the AGC kinase family with established roles in cytokinesis, central nervous system (CNS) development, and cancer progression." (PMID 41601480, 2026). "Among the cancer driver genes that experienced epigenetic changes in at least five cancer types, we identified eight genes: CEP55, PIF1, RRM2, NCAPH, ZEB2, CIT, FLI1, and PCDH17." (PMID 31900418, 2020).
tumor (12 papers, 2012 to 2026). "Previous studies have found that p27 acts as a tumor suppressor by closely binding to CIT to prevent its interaction with its activator RhoA, thereby regulating cytokinesis." (PMID 34305997, 2021). "Analysis of ChIP sequencing data (GSE56288) for the recruitment of HOXB13 and AR to the vicinity of the CIT/STK21 revealed overlapping peaks, consistent with our original selection for tumor-specific ARBS." (PMID 31273254, 2019). "Gene alterations associated with tumor grade progression in initial low grade tumors include FBN3, CIT and HECTD4." (PMID 29507699, 2018). "Taken together, these findings suggest that targeting CIT may serve as a potential anti-tumor treatment for a variety of cancers." (PMID 34305997, 2021). "This analysis revealed that CIT knockdown significantly reduced tumor volume." (PMID 29069760, 2017). "Similar to what we observed in cultured cell lines, CRISPR-mediated suppression of CIT or ZFHX3 led to the reduction in expression of the target and tumour size." (PMID 33499898, 2021).
adenocarcinoma (1 paper, 2017). A common cancer characterized by the presence of malignant glandular cells. "Notably, 4 of the glucose metabolism-related genes, GPI, G6PD, PKM2, and GAPDH and 5 of the cell cycle-related genes, ANLN, PTTG1, CIT, KPNA2, and CDC25A, were significantly down-regulated in EGFR m+ adenocarcinomas, and showed a substantial correlation with SUVmax." (PMID 28422979, 2017).
CIT also shares sentences with these, for which no sentence is quoted: multiple myeloma (3 papers); esophageal cancer (2); microlissencephaly (2); schizophrenia (2); autosomal recessive primary microcephaly (1); cervical cancer (1); colorectal cancer (1); glioma (1); infection (1); Intellectual disability (1); metastatic prostate carcinoma (1); movement disorder (1); neuroblastoma (1); neurodevelopmental disorder (1); osteosarcoma (1); ovarian carcinoma (1); pancreatic ductal adenocarcinoma (1); promyelocytic leukemia (1); Salmonella Infections (1); urothelial carcinoma (1).